IGFBP3 (insulin like growth factor binding protein 3)
Diseases named in the same sentence as IGFBP3 in open-access papers (continued):
Sharing a sentence is not in itself a finding about the gene and the disease.
melanoma (24 papers, 2007 to 2025). A malignant, usually aggressive tumor composed of atypical, neoplastic melanocytes. "In pancreatic endocrine (i.e., islet cell) neoplasms and melanoma, high tumor IGFBP-3 levels by IHC are associated with increased metastasis, but again the staining is predominantly cytoplasmic." (PMID 29623068, 2018). "When assessed for co-expression of VN and IGFBP-3, we found IGFBP-3:VN interactions predominantly in malignant melanoma and SCC patient tumors, and mainly tumor-cell associated." (PMID 29330502, 2018). "Upon the whole, the present data confirmed and reinforced our previous surmise that melanoma progression is significantly correlated with loss of seric IGFBP-3." (PMID 24905466, 2014). "The serum levels of IGFBP-3 in patients with melanoma are significantly reduced, and a low IGFBP-3 level is associated with metastasis and cancer progression, while IGFBP-3 administration can significantly inhibit the migration and invasion of different melanoma cell lines." (PMID 35356065, 2022). "C2 IGFBP3+, which had the lowest CytoTRACE2 score and was enriched in late tumor stages, affected melanoma development." (PMID 41383633, 2025). "In conclusion, we identified a distinct, predicted-immunoregulatory IGFBP3+ melanoma cell subtype and established FOSL1 as a key oncogenic driver within this subtype." (PMID 41383633, 2025). "Potential studies incorporating spatial transcriptomics or multi- omics approaches that include cerebral markers are necessary to instantly map the geographical relationship between the C2 IGFBP3+ subtype, nerves and immune cells within the melanoma TME." (PMID 41383633, 2025). "We analyzed the differential expression levels of stemness-related genes among different subtypes and groups, revealing that KLF4 was markedly elevated in the C2 IGFBP3+ melanoma cells." (PMID 41383633, 2025). "We identified immunoregulatory C2 IGFBP3+ melanoma cell subtypes in our investigation, and FOSL1 was a crucial transcription factor that aided in cell migration, proliferation, and survival." (PMID 41383633, 2025). "This is in line with previous studies in CM demonstrating that downregulation of IGFBP3 promotes melanoma cell survival, proliferation and invasion via phosphorylation of AKT." (PMID 37179302, 2023). "Its anti-tumor effect is due to inhibition of the Wnt pathway; thus, IGFBP3 treatment is an attractive potential therapeutic approach for melanoma." (PMID 35958518, 2022). "IGF-I:IGFBP-3:VN trimeric (TRI) complex-stimulated melanoma cell proliferation and migration was assessed using the MTS cell proliferation and Transwell migration assays." (PMID 29330502, 2018). "In melanoma all three components of the IGF-I:IGFBP:VN complex are independently shown to be associated with different stages of the disease, wherein IGF-I:IGFBP-3 would more likely be associated with ECM proteins like VN and not present in “solution”." (PMID 29330502, 2018). "Peptide antagonists designed to target the binding of IGF-I:IGFBP-3 to VN were demonstrated to inhibit IGF-I:IGFBP-3:VN-stimulated cell migration, invasion and 3D tumor cell growth of melanoma cells." (PMID 29330502, 2018). "Although evidence exists for the role of individual components of the complex (IGF-I, IGFBP-3 and VN), the cellular functions stimulated by these proteins together as a complex remains un-investigated in melanoma cells." (PMID 29330502, 2018). "IGFBP-3-induced proliferation arrest and apoptosis induction were described by other investigators on tumors other than melanoma, but to the best of our knowledge inhibition of cell motility and invasiveness has not been reported previously." (PMID 24905466, 2014). "The p38 kinases, which have been reported to stimulate the migratory and growth capacity of melanoma cells, remained unaffected by IGFBP-3 treatment." (PMID 24905466, 2014). "In this study we show that IGFBP-3 has a remarkable anti-tumoral activity on malignant melanoma, both in vitro and in vivo." (PMID 24905466, 2014).
melanoma (continued). "In agreement with a previous study, clinical observations revealed that IGFBP-3 serum levels of melanoma patients were highly correlated with disease stage and progression." (PMID 24905466, 2014). "In a previous work, we showed that serum levels of IGFBP-3 are lowered significantly in stage-IV melanoma patients." (PMID 24905466, 2014). "In fact, we show here that the IGFBP-3 content of melanomas and their tissutal environment becomes progressively lower with advancing disease, and that IGFBP-3 loss is accompanied by a parallel increase in MMP-9." (PMID 24905466, 2014). "In a previous report, we have shown that a strong correlation exists between the serum concentration of full-size, glycosylated IGFBP-3 and disease progression in melanoma patients." (PMID 24905466, 2014). "It is possible, therefore, that melanomas ingrain a self-sustaining loop, destroying IGFBP-3 as they grow and becoming as a consequence ever more aggressive." (PMID 24905466, 2014). "Work is in progress to specifically assess the in vivo effect of IGFBP-3 on melanoma metastatic spread." (PMID 24905466, 2014). "The IGFBP3 gene, known to be hypermethylated in melanoma and other cancers, was used as a positive control and was highly expressed upon 5-aza-dC treatment." (PMID 22948084, 2012). "We examined the expression of IGFBP-3 and -4 in primary melanomas from 72 primary patients, according to 6th Edition of the AJCC staging guidelines." (PMID 19025658, 2008). "In this study, we examined both IGFBP-3 and -4 levels in tissues and sera of melanoma patients representing different stages of melanoma progression." (PMID 19025658, 2008). "The prognostic relevance of IGFBP-3 or -4 expressions in melanoma also requires further investigation." (PMID 19025658, 2008). "We examined the expression of IGFBP-3 and -4 in 60 melanoma tumors from 60 patients with metastatic disease according to 6th Edition of the AJCC staging guidelines." (PMID 19025658, 2008). "In fact, IGFBP-3 sera levels of the majority of the melanoma patients fell within the normal expected range for adults." (PMID 19025658, 2008). "Median IGFBP-3 expression in primary melanoma tumor specimens was 80%, while median IGFBP-4 expression in primary tumors was 70%." (PMID 19025658, 2008). "Our melanoma invasion signature is associated with upregulation of critical NF-κB effectors including CXCL1, FMN2, MMP1, IL-8, IGFBP3 which have been implicated in the regulation of tumor cell proliferation, motility, migration, and/or invasion." (PMID 17611626, 2007). "Interestingly, studies in melanoma demonstrate that in early phases of tumor growth and metastasis where IGFBP-3 expression is reduced due to promoter hypermethylation, elevated IGFBP-3 inhibits Wnt/β-catenin signaling, reducing metastatic potential." (PMID 41226289, 2025). "However, during late-stage growth in highly metastatic melanoma cell lines, IGFBP-3-promoted cell migration and knockdown reduced cell motility." (PMID 41226289, 2025). "Furthermore, we reveal IGFBP-3:VN protein complexes in malignant melanoma and squamous cell carcinoma patient tissues, where the IGFBP-3:VN complex was seen to be predominantly tumor cell-associated." (PMID 29330502, 2018). "However, IGFBP3 has also been shown to have an oncogenic potential with drastic increase in expression in cultured human melanoma cells." (PMID 28223541, 2017). "There is also evidence of IGFBP-3 being associated with metastatic disease, with IGFBP-3 expression elevated in metastatic tissue compared with primary tumor in melanoma, and higher in metastatic than nonmetastatic tumors in pancreatic endocrine neoplasms." (PMID 26221601, 2015). "The progression of primary melanoma to metastatic disease may be influenced by the IGFBP-3 in the tissutal microenvironment." (PMID 24905466, 2014). "Finally, we show that recombinant human IGFBP-3 is also able to strongly reduce melanoma growth in mouse models in vivo." (PMID 24905466, 2014).
melanoma (continued). "Notably, an inverse correlation has been observed between the amount of IGFBP-3 produced by melanoma tissue and the metastatic capacity of the cells." (PMID 24905466, 2014). "This may suggest that melanomas have an active role in destroying IGFBP-3, and indeed many tumors are known to produce proteases." (PMID 24905466, 2014). "In this study, we have assessed the clinicopathologic relevance of circulating as well as tumor-specific levels of IGFBP-3 and -4 in melanoma and aimed to define the most clinically relevant test to be integrated in correlative studies of clinical trials targeting IGF." (PMID 19025658, 2008). "In particular the most significant up-regulated gene IGFBP3 is intriguing in the context that another member of the insulin-like growth factor binding protein family, IGFBP7 has recently been implicated as an inducer of apoptosis in human melanoma cell lines." (PMID 18714388, 2008). "However, the alternative hypothesis that melanomas inhibit tissutal, or even hepatic, production of IGFBP-3 cannot yet be discounted and is currently being tested." (PMID 24905466, 2014). "Moreover, low IGFBP-3 was highly correlated with survival and metastatic volume, suggesting that lack of this protein in the blood accompanies, and perhaps favours, metastatic dissemination of melanoma." (PMID 24905466, 2014). "In summary, IGFBP-3 appears to exert a specific inhibitory effect on melanoma growth and dissemination, suggesting that it may qualify as a useful therapeutic agent in melanomas and perhaps other cancers, at the least as a valid adjuvant therapy during treatment with conventional anti-tumoral drugs." (PMID 24905466, 2014). "Interestingly, nearly 30% of patients studied (10 primary, 15 metastatic patients) had IGFBP-3 sera concentrations up to twice the expected normal maximum, and 5 of the 15 metastatic patients with high serum IGFBP-3 died of melanoma less than 2 years after the date of blood collection." (PMID 19025658, 2008). "Our recognition of the immunoregulatory C2 IGFBP3+ subtype, predicted to act as a source of MHC-II and PROS pathways, raises questions about its potential role in the neuro-immune axis of melanoma." (PMID 41383633, 2025). "Solid‐state antibody chip results, including 105 antibodies, showed that GC‐7 and GL‐1 affected the expression of melanoma cytokines, among which ANG, IGFBP3, CSF2, CD71, CXCL1, and MMP9 were the most significant." (PMID 38952061, 2024). "IGFBP3-mediated IGF1R activation was first observed in erlotinib-treated PC9 cells, and a similar mechanism was also described in BRAF (V600E) melanoma cells adapting to targeted BRAF inhibition." (PMID 38473364, 2024). "We report here that the IGF-I:IGFBP-3:VN trimeric complex stimulates a dose-dependent increase in the proliferation and migration of WM35 and Sk-MEL28 melanoma cells." (PMID 29330502, 2018). "IGF-binding proteins 2 (IGFBP2) and 3 (IGFBP3) were expressed at relatively high levels in SK-MEL-28 (Figure 5a1) and are known to have differential roles in melanoma progression." (PMID 28223541, 2017). "Trans-well-migration/invasion assays revealed that the invasive capacity of metastatic melanoma cells was also strongly impaired by treatment with IGFBP-3, while being enhanced by treatment with anti-IGFBP-3 antibodies." (PMID 24905466, 2014). "The anti-tumoral effect of IGFBP-3 was also investigated in vivo using a murine model, namely SCID mice which were inoculated with human melanoma (Me501) cells." (PMID 24905466, 2014). "Realtime PCR revealed a significantly higher expression of FOSL1, OPN, IGFBP3, DUSP4 and TAAL6 in most of the melanoma cell lines compared to normal melanocytes." (PMID 20663135, 2010). "At the level of protein, NHEM displayed almost no expression of most of the proteins, whereas in the majority of examined melanoma cell lines FOSL1, IGFBP3 and DUSP4 were strongly expressed." (PMID 20663135, 2010).
melanoma (continued). "Although sera shedding of IGFBP-3 increased slightly in the progression from primary to metastatic melanoma, the majority of IGFBP-3 sera levels in the melanoma patient cohort fell within the expected range for healthy adults (1.5–5.6 ug/ml)." (PMID 19025658, 2008). "On the other hand, the role of the IGFBP3 gene in cancer is not entirely understood, because both melanoma-supporting and inhibiting effect was shown concerning this factor." (PMID 33182777, 2020). "Interestingly, we observed consistent expression of GH transcript in the melanoma cells as well as marked modulation of the IGF receptors and binding proteins (IGF1R, IGF2R, IR, IGFBP2, IGFBP3) and the oncogenic HGF-MET mRNA, in response to excess GH or GHRKD." (PMID 28223541, 2017). "IGFBP-2, IGFBP-3 and IGFBP-7 expression was elevated in epithelial-like melanoma cells." (PMID 25940796, 2015). "The WM793 primary-melanoma cells, which have a relatively high proliferation rate but are scarcely mobile or invasive, did not respond to IGFBP-3 either at the phenotypic or at the molecular level." (PMID 24905466, 2014). "The same relationship held for the ratio IGF-1/IGFBP-3, while the IGF-1 levels per se did not correlate with melanoma stage, suggesting that the apparently protective function of IGFBP-3 is not limited to preventing IGF-1 from stimulating cell proliferation." (PMID 24905466, 2014). "Importantly, we found that FOSL1, OPN, IGFBP3, DUSP4, and TAAL6 also exhibited increased expression levels in human melanoma cell lines compared to human melanocytes." (PMID 20663135, 2010). "Importantly, the signaling networks employed by the C2 IGFBP3+ subtype, particularly the PROS and MHC-II pathway, suggest a potential, unexplored role for this aggressive subtype in mediating neuro-immune crosstalk within the melanoma microenvironment." (PMID 41383633, 2025). "Therefore, IGFBP-3:VN complexes were investigated using the in situ proximity ligation assay (PLA) in normal skin, squamous cell carcinoma (SCC), basal cell carcinoma (BCC) and malignant melanoma (MM) tissue sections." (PMID 29330502, 2018). "Indeed, tyrosinase activity measured on lysates of tumour tissues was higher in the tumours excised from IGFBP-3-treated mice, confirming the observations made on cultured melanoma cells (not shown)." (PMID 24905466, 2014). "Furthermore, IGFBP3 has been shown to suppress migration and invasion in adult HCC and melanoma." (PMID 22401581, 2012). "However, data do not support the clinical utility of measuring levels of IGFBP-3 and -4 in sera of melanoma patients." (PMID 19025658, 2008).
type 2 diabetes (24 papers, 2012 to 2025). "We sought to investigate the association of IGF-1 and IGFBP-3 with cardio-renal outcomes among persons with type 2 diabetes." (PMID 37438734, 2023). "It is of importance to follow-up on these observations and clarify whether such changes in circulating IGFBP3 levels could influence susceptibility of developing type 2 diabetes and modulate cancer risk later in life." (PMID 29947889, 2018). "A positive effect of As on IGFBP3 concentrations could potentially explain in part the epidemiological association between exposure to As and type 2 diabetes that was put forward by a meta-analysis." (PMID 29947889, 2018). "Clinical studies showed that IGFBP-3 is down-regulated in Type 2 Diabetes patients with renal disfunction, and predict future renal decline in people with type 2 diabetes combined with apoA4 and CD5L." (PMID 35002740, 2021). "For example, PR3 is suggested to directly link inflammation to type 2 diabetes through the downregulation of insulin-like growth factor-1/IGFBP3." (PMID 31935243, 2020). "The analysis of sialylation of insulin-like growth factor-binding protein (IGFBP)-3 from the poorly controlled patients with type 2 diabetes, increased binding of IGFBP-3 to SNA suggesting increased sialylation of IGFBP3." (PMID 24143207, 2013). "The role of IGFBP-3 in type 2 diabetes and its complications requires further consideration." (PMID 37438734, 2023). "This hypothesis is consistent with previous studies in which type 2 diabetes has been associated with abnormalities in SQ AT levels of the IGF-1 receptor and IGFBP3." (PMID 26067361, 2015). "In this trial of patients with type 2 diabetes and CKD who were randomized to receive canagliflozin or placebo, we showed that baseline IGF-1 levels and IGF-1/IGFBP-3 ratio (but not IGFBP-3 concentrations) were associated with cardio-renal outcomes." (PMID 37438734, 2023). "The OR estimate for type 2 diabetes did not change after exclusion of three SNPs in the IGFBP3 or IGF2 gene regions." (PMID 32548700, 2020). "Moreover, PRTN3 has been proposed as an inflammatory enzyme able to digest insulin-like growth factor 1 (IGF-1) and the insulin-like growth factor-binding protein-3 (IGFBP3) and promote glomerular inflammation in type 2 diabetes." (PMID 25874235, 2015). "Furthermore, a lower serum IGF-1/IGFBP-3 molar ratio has been connected to poorer executive function in MCI patients, particularly those with type 2 diabetes mellitus (T2DM), suggesting that IGF-1 may play a role in the development of cognitive impairment." (PMID 40699632, 2025). "As far as we know, two previous studies in humans, with small sample size (n = 39–40), examined protein or gene expression of the IGF1, IGF2, IGFBP3, INSR, IGF1R and downstream targets IRS1, IRS2 and mTOR in women with or without type 2 diabetes." (PMID 29486734, 2018).